MYH7 (myosin heavy chain 7)
Description:
Myosins are actin-based motor molecules with ATPase activity essential for muscle contraction. Forms regular bipolar thick filaments that, together with actin thin filaments, constitute the fundamental contractile unit of skeletal and cardiac muscle.
Synonyms: MYHCB; CMD1S; CMH1; CMYO7A; CMYO7B; CMYP7A; CMYP7B; MPD1; SPMD; SPMM
Tractability: Small molecule: an approved drug acts on it; a structure with a bound ligand is known. PROTAC: ubiquitination databases record sites on it.
Gene: Protein-coding gene on chromosome 14 (23,412,733 to 23,436,137, reverse strand). Ensembl gene ENSG00000092054.
Subcellular location: Cytoplasm, myofibril; Cytoplasm, myofibril, sarcomere
Subcellular location (Human Protein Atlas): Focal adhesion sites
Gene Ontology:
Molecular function: microfilament motor activity; protein binding; actin filament binding; ATP binding; cytoskeletal motor activity
Biological process: adult heart development; ATP metabolic process; cardiac muscle contraction; muscle contraction; muscle filament sliding; regulation of heart rate; regulation of slow-twitch skeletal muscle fiber contraction; regulation of the force of heart contraction; regulation of the force of skeletal muscle contraction; skeletal muscle contraction; striated muscle contraction; ventricular cardiac muscle tissue morphogenesis
Cellular component: myosin filament; cytoplasm; muscle myosin complex; myofibril; myosin complex; myosin II complex; sarcomere; stress fiber; supramolecular fiber; Z disc
Genetic constraint (gnomAD): Loss-of-function variants: 129 observed, 231.92 expected, observed/expected ratio (o/e) 0.56, 90% interval 0.48 to 0.64. The upper end of that interval is the gene's LOEUF score, 0.64, which puts it in group 2 of 6, group 1 being the genes least tolerant of losing a copy. Missense variants: 1,649 observed, 2,599 expected, observed/expected ratio (o/e) 0.63, 90% interval 0.61 to 0.66. Synonymous variants: 971 observed, 1,042.4 expected, observed/expected ratio (o/e) 0.93, 90% interval 0.88 to 0.98.
Gene-disease validity (ClinGen):
ClinGen rates the evidence that MYH7 causes each of these diseases.
dilated cardiomyopathy 1S (autosomal dominant): Definitive.
hypertrophic cardiomyopathy (autosomal dominant): Definitive. A condition in which the myocardium is hypertrophied without an obvious cause.
MYH7-related skeletal myopathy (autosomal dominant): Definitive.
arrhythmogenic right ventricular cardiomyopathy (autosomal dominant): Limited.
congenital heart disease (autosomal dominant): Limited. A heart disease that is present at birth.
Homologues: Orthologues: chimpanzee MYH7 (99% identical), rabbit MYH7 (98% identical), rat Myh7 (98% identical), mouse Myh7 (98% identical), macaque MYH7 (97% identical), guinea pig MYH7 (97% identical), pig MYH7 (96% identical), dog MYH7 (93% identical), zebrafish myh7l (86% identical). Paralogues in human: MYH6 (93% identical), MYH1 (81% identical), MYH2 (81% identical), MYH4 (81% identical), MYH8 (81% identical), MYH3 (79% identical), MYH13 (77% identical), MYH7B (70% identical), MYH15 (62% identical), MYH9 (42% identical), MYH10 (42% identical), MYH11 (42% identical), and 32 more.
Diseases named in the same sentence as MYH7 in open-access papers:
MYH7 is named in the same sentence as 184 diseases in open-access papers, as found by Europe PMC text mining. Sharing a sentence is not in itself a finding about the gene and the disease. The quoted sentences say what the papers report.
cardiac hypertrophy (184 papers, 2012 to 2026). "Abnormal expression of fetal genes, such as Myh7 or Myh3, has been associated with cardiac hypertrophy during cardiac development." (PMID 41509912, 2026). "DSH cats carrying the heterozygous E1883K variant in MYH7, a variant present in humans, showed impaired relaxation, cardiac hypertrophy, fibrosis, and myocardial disarray." (PMID 40306862, 2025). "It upregulates the expression of myosin heavy chain-7 (MyHC7) which is closely associated with cardiac hypertrophy, cardiomyopathy, and acute myocardial infarction." (PMID 40672362, 2025). "In preclinical models, CRISPR-Cas9 has shown promise in correcting HCM-associated mutations in β-myosin heavy chain 7 (MYH7), preventing disease phenotypes such as ventricular hypertrophy and myocardial fibrosis." (PMID 40130092, 2025). "Bulk RNA sequencing revealed significant upregulation of several biomarkers associated with cardiac hypertrophy in BubR1 hypomorphic hearts, including Thbs4, Acta1, Tnni2, and Myh7." (PMID 40607964, 2025). "The MYH7 R453C mutant not only developed cardiac hypertrophy remodelling, but also severe pathological fibrosis and loss of cardiomyocytes, while the MYH6 R453C mutant showed milder HCM characteristics." (PMID 38862020, 2024). "Hypertrophic cardiomyopathy (HCM) is caused by myocardial hypertrophy, often due to mutations in cardiac sarcomere protein genes such as beta-myosin heavy chain (MYH7) and myosin-binding protein C (MYBPC3)." (PMID 39165751, 2024). "Patients with HCM harboring MYH7 variants exhibited severe ventricular hypertrophy and ventricular exacerbation when compared with those harboring other genetic variants." (PMID 37904158, 2023). "Upregulation of Myh7 and Bnp transcriptional activity is an indication of the risk for developing cardiac hypertrophy." (PMID 36998980, 2023). "Considering that Nppa, Nppb and Myh7 are not only embryonic marker genes but also markers of cardiac hypertrophy, we infer that Hmgcs2 knockout causes cardiac stress, but does not affect cardiac development." (PMID 36220812, 2022). "Since myocardial hypertrophy is a hallmark of HF, some of the classical markers of cardiac hypertrophy (Bnp and Myh7) were assessed in the H9c2 cells stimulated with the neurohormonal stimuli (Ang II and/or Nor)." (PMID 34001233, 2021). "MHCβ expression is higher in the developing embryonic heart, and higher expression of myh7 in the adult heart is one of the major causes of cardiac hypertrophy." (PMID 34207151, 2021). "Sarcomeric cardiac β-myosin heavy chain gene (Myh7) has been shown to be associated with myocardial hypertrophy." (PMID 34745139, 2021). "Myh7, a myosin heavy chain associated RNA transcript (Mhrt) was irreversibly reduced after the induction of cardiac hypertrophy through transverse aortic surgery (TAC)." (PMID 32455975, 2020). "Mhrt is downregulated in the mouse heart with thoracic aortic constriction (TAC)-induced cardiac hypertrophy and was associated with the Myh6/Myh7 isoform switch, a pathognomonic signature of cardiomyopathy." (PMID 32241300, 2020). "We evaluated expression of atrial natriuretic factor (Nppa) and β-Myosin heavy chain 7 (Myh7), known to be associated with cardiac hypertrophy." (PMID 32973791, 2020). "Maternal obesity caused the upregulation of Nppa and Myh7 in cardiac tissue of adult male offspring, concurrent with other markers of pathologic cardiac hypertrophy including increased heart weight and cardiomyocyte cell area." (PMID 30293577, 2018). "MYH7 is a hallmark of cardiac hypertrophy, and the switch in MYH6:MYH7 expression ratio is linked to cardiac hypertrophy and heart failure." (PMID 28752208, 2017). "Additionally, mice with Lgr6 deficiency showed upregulated expression levels of cardiac hypertrophy‐related markers, including Nppa, Nppb, and Myh7, suggesting that Lgr6 deficiency exacerbates PO‐induced cardiac hypertrophy." (PMID 40211903, 2025).
cardiac hypertrophy (continued). "By quantitative RT-PCR, we found that hearts from the TAC-operated Corin KO mice had increased levels of Nppa, Nppb, Myh7, which were associated cardiac hypertrophy, and Ctgf, which was associated with cardiac fibrosis, compared with those in the sham-operated Corin KO mice." (PMID 37636304, 2023). "Furthermore, the increase in Nppa and Myh7 expression (associated with cardiac hypertrophy) after TAC was significantly attenuated in DBZ-treated rats." (PMID 35185583, 2022). "The mice had a heart phenotype similar to hypertrophic cardiomyopathy that was recapitulated in multiple instances, which reported defective myocyte function and development of cardiac hypertrophy and lethal cardiomyopathy in mice bearing an p.Arg403Gln Myh7 variant." (PMID 31783775, 2019). "In addition, GLA-null CMs were characterized by shifted balance between α- and β-cardiac myosin heavy chain (MYH6/MYH7 ratio) expression, which is a common response to cardiac injury and a hallmark of cardiac hypertrophy." (PMID 30965672, 2019). "In the present study we demonstrate that transcriptional reprogramming of Atp2a2 and Myh7 genes in pressure overload-induced cardiac hypertrophy and failure is associated with significant epigenetic changes, modifying chromatin dynamics at the promoter regions of these crucial genes." (PMID 25181347, 2014). "To further investigate whether this cardiac histological change was physiological or pathological, we examined the expression of four genes associated with pathological cardiac hypertrophy, including Myosin heavy chain 6 (Myh6), Natriuretic Peptide A (Nppa), Nppb, and Myh7." (PMID 41460785, 2025). "LVETI was lower in the MYBPC3 than in the MYH7 group despite similar degrees of cardiac hypertrophy, outflow tract obstruction and LVEF." (PMID 40613316, 2025). "We found that tRF-Glu-CTC-013 significantly reduced the Ang II-induced increase in cardiomyocyte surface area, as well as reducing the expression of the cardiac hypertrophy markers Nppa, Nppb and Myh7." (PMID 40520901, 2025). "Deficiency of myeloid MR in diabetic hearts reduced the increase in myocyte size by 35% and inhibited elevated gene expressions of Myh7 by 40%, indicating suppression of cardiac hypertrophy." (PMID 41332229, 2025). "We detected an increase in biomarker mRNA expression indicative of cardiac hypertrophy, specifically Myh6 and Nppa, while the levels of Myh7 and Nppb remained unchanged." (PMID 40463063, 2025). "The Ang II-induced cardiac hypertrophy markers Nppa, Nppb, and Myh7 were significantly increased in the Ang II group." (PMID 40520901, 2025). "Of note, Ca2+/calcineurin signaling has been shown to promote Myh7 mRNA expression in mouse model of cardiac hypertrophy." (PMID 39948277, 2025). "AngII caused hypertension and up-regulated the expression of genes contributing to pathological cardiac hypertrophy (Nppa, Myh7) more severely so in foz/foz mice than in controls." (PMID 39206703, 2024). "The re-expression of foetal Myh7 with concomitant down-regulation of Myh6 is a well-known characteristic of pathological cardiac hypertrophy in rodents." (PMID 39206703, 2024). "Consistent with their enlarged hearts, dKO mice showed significant increases in the expression of the cardiac hypertrophy genes Acta2 (P≤0.05) and Myh7 (P≤0.0005)." (PMID 38770680, 2024). "A lower expression of Nppa, Nppb, a lower Myh7/Myh6 RNA ratio, and a reduced CM cross-sectional area confirmed blunted cardiac hypertrophy in Gadlor-KO animals compared with WT littermates after TAC." (PMID 39281699, 2024). "Biomarkers of cardiac hypertrophy, such as Anp, Bnp, and Myh7, were also significantly increased in the siTEAD1 group compared to those in the siControl group." (PMID 38225750, 2024). "The mRNA levels of genes related to cardiac hypertrophy (Anp, Bnp, and Myh7) and fibrosis (Col1a1, Col3a1, and Ctgf) were upregulated in AAV‐TEAD1‐K177R mice." (PMID 38225750, 2024).
cardiac hypertrophy (continued). "Quantitative reverse transcription-PCR analysis showed that the mRNA expression of myosin heavy chain-7, a cardiac hypertrophy marker, significantly increased in the heart tissue of the mRNA-administered groups with or without the LPS pump." (PMID 38360752, 2024). "Expressions of cardiac hypertrophy marker genes Myh7 and Myh6 were dysregulated upon MI surgery and partially restored by CPX treatment." (PMID 36826549, 2023). "Increased superoxide and hydrogen peroxide generation in endothelial cell BH4-deficient hearts is consistent with the induction of fetal gene expression (nppa, nppb, and myh7) contributing to cardiac hypertrophy." (PMID 36735402, 2023). "This study also observed that following rapamycin addition to inhibiting the activity of mTOR activity, the effect of Apelin-13 on improving cardiac hypertrophy was significantly reduced and that the expression of MYH7 was significantly increased." (PMID 36742144, 2023). "Carvacrol significantly improved blood glucose levels, cardiac fibrosis and reversed cardiac hypertrophy, Myh7, and Nppa mRNA expressions." (PMID 36348778, 2022). "Both AngII group and TAC group showed that the expression levels of Myh7, Anp, and Bnp, which can reflect the degree of myocardial hypertrophy, were significantly increased." (PMID 35211156, 2022). "mRNA expression of cardiac hypertrophy marker genes Nppa, Nppb, Myh6, and Myh7 was massively enhanced compared with genes in control mice on P25." (PMID 35167494, 2022). "We mined the data for classical markers of cardiac hypertrophy and detected increased expression of Myh7, Nppa and Nppb with AngII as expected, but expression was similar in Pkn2Het and WT mice." (PMID 35730579, 2022). "Given that similarly expressed genes, such as Nppa, Nppb, and Myh7, function in cardiac hypertrophy and HF23–25, we further analyzed the lncRNA trapped in this line." (PMID 33953175, 2021). "Next generation sequence (NGS) analysis indicated a modulation of the expression levels of several cardiac hypertrophy-associated genes, including GPR22, Myh7, Nppa, P2RX4, and Npy by MFE." (PMID 34579143, 2021). "Among the identified proteins by mass spectrometry, MYH7 (beta-myosin heavy chain) has been reported as an important cardiac hypertrophy marker." (PMID 34266473, 2021). "The relative expression levels of cardiac hypertrophy-related genes, such as βmhc and Myh7, were increased in both groups after TAC and were higher in the SKO-TAC group than in the WT-TAC group (P < 0.05 and P < 0.01, respectively)." (PMID 33778025, 2021). "Collectively, these results indicate that YTHDF2 interacting with Myh7 mRNA via YTH domain to alleviate cardiac hypertrophy." (PMID 34266473, 2021). "As ANP, BNP, and MYH7 are all classic biomarkers of cardiac hypertrophy, we also detected their expressions in heart tissues of rats from different groups." (PMID 34336950, 2021). "Myh-7 and Nppa are wildly used as markers for cardiac hypertrophy and pressure overload, while P2RX4 is considered to play a beneficial role in alleviating cardiac hypertrophy and heart failure in a canine calsequestrin (CSQ) transgenic mouse model." (PMID 34579143, 2021). "Administration of SPRC to db/db mice decreased HW/TL ratios and cardiomyocyte cross-sectional area, reduced mRNA level of beta-myosin heavy chain (Myh7) gene, marker for cardiac hypertrophy." (PMID 34604360, 2021). "cardiac hypertrophy, cancer, cell death and survival with upregulation of proteins such as MYH7, MYL2, APOA1 and phospholamban (Table of Top enriched networks from core analysis of both H9c2 and GK overexpressed proteins S1 Table)." (PMID 34166385, 2021). "Cardiac hypertrophy markers, such as Nppa, Nppb, and Myh7, were also upregulated by Sp1 overexpression." (PMID 34462460, 2021). "To validate the neurohormonal activation cell model, we analyzed the expression of cardiac hypertrophy molecules (Bnp and Myh7) as hallmarks of HF." (PMID 34001233, 2021).
cardiac hypertrophy (continued). "Overall, our results indicate that the m6A Reader YTHDF2 suppresses cardiac hypertrophy via Myh7 mRNA decoy in an m6A-dependent manner." (PMID 34266473, 2021). "In this study, we find that YTHDF2 suppresses cardiac hypertrophy through regulating Myh7 mRNA decoy in vitro using the primary mice cardiomyocytes stimulated with ISO or PHE, and in vivo using TAC mouse model." (PMID 34266473, 2021). "In conclusion, out study explores the role of YTHDF family proteins during HF development, and indicates YTHDF2 suppresses cardiac hypertrophy and HF via Myh7 mRNA decoy in an m6A-dependent manner." (PMID 34266473, 2021). "We also showed increased expression of Myh7, which codes for the β‐myosin heavy chain, a well‐known marker of cardiac hypertrophy that has also been localized to areas of fibrosis in the heart." (PMID 34713972, 2021). "Knockdown of Myh7 or deletion of the YTH domain of YTHDF2 reversed the protective effects of YTHDF2 on cardiac hypertrophy." (PMID 34266473, 2021). "Subsequent RT-PCR indicated that MFE regulated the expression levels of genes responsive to cardiac hypertrophy (i.e., Myh-7, ANP) and oxidative stress (i.e., GR, GPx, and NQO-1)." (PMID 34579143, 2021). "A cluster of lncRNAs from the Myh7 gene was identified as functionally significant in cardiac hypertrophy in mice." (PMID 32455975, 2020). "Our pilot analysis of other cardiac mRNAs shows a concurrent induction of transcripts of cardiac hypertrophy genes Nppa and MyH7 by heme in the heart of SS mice." (PMID 32973791, 2020). "mRNA expression analysis revealed activation of molecular profiles of cardiac hypertrophy with increased fetal cardiac gene expression, i.e., Nppa, Nppb, Myh7, and decreased Myh6 expression." (PMID 33203971, 2020). "At the end of the treatment period, both T1DM and T2DM mice showed lesser cardiac hypertrophy, Nppa and Myh7 mRNA expressions, and cardiac fibrosis, compared to mice administered only the vehicle." (PMID 31572181, 2019). "Transcription of myosin heavy chain α (MYH6) and β (MYH7), defined markers for myocardial hypertrophy, resembled this predominant obesity‐induced effect on cardiac remodelling." (PMID 31368189, 2019). "Heart samples from hypertrophic cardiomyopathy patients exhibited elevated expression of genes related to pathological cardiac hypertrophy, such as Nppa, Nppb, and Myh7 (Fig EV1A)." (PMID 31532577, 2019). "FNDC5 overexpression alleviated HFD-induced cardiac hypertrophy evidenced by reduced Nppa, Nppb, Myh7 mRNA level and cardiomyocytes area." (PMID 30940158, 2019). "Further, in cardiac hypertrophy an elevation of Myh7 can serve as an early and sensitive marker and recently downregulation of Myh6 expression in human hearts was observed, too." (PMID 30564194, 2018). "It should be noted, that in mouse models of cardiac hypertrophy, a 2-fold overexpression of the MYH7-gene is considered to be an early marker of hypertrophic development." (PMID 29555974, 2018). "Emerging evidence demonstrated that MYH7 protein expression was significantly increased in cardiac hypertrophy and has been identified as hypertrophy-related marker." (PMID 28479925, 2017). "Cardiac hypertrophy was also evidenced by the gradual increase in Myh7 and decrease in Myh6 at mRNA level." (PMID 27731386, 2016). "For example, we observed deregulation of chamber-specific factors (e.g. Myh7, Bmp7, Anf, Acta1, Egr1 and Fos) that are also upregulated in adult cardiac hypertrophy and/or heart failure." (PMID 25803368, 2015). "We observed by real-time PCR an up-regulation of Myh7 gene expression which is consistent with the phenotype of cardiac hypertrophy observed." (PMID 24475304, 2014). "To test this possibility, we used a well-established mouse model of cardiac hypertrophy and HF induced by transverse aortic constriction, and analyzed chromatin marks at the Atp2a2 and Myh7 promoters after one or eight weeks of pressure overload." (PMID 25181347, 2014).